APOE (apolipoprotein E)
Diseases named in the same sentence as APOE in open-access papers (continued):
Sharing a sentence is not in itself a finding about the gene and the disease.
Alzheimer disease (continued). "Having one copy of the e4 variant of the APOE gene (APOE-e4) is associated with increased risk and earlier onset age of Alzheimer disease dementia, and the 1%–2% of the population who carry two copies of this variant (APOE-e4/e4) are at especially increased risk." (PMID 28323826, 2017). "The apolipoprotein ε4 allele (APOE ε4 allele) it is strongly associated with detrimental outcomes to adult health including high cholesterol, atherosclerotic disease, reduced lifespan and Alzheimer’s disease (AD)." (PMID 28683096, 2017). "The ε4 allele of the apolipoprotein E gene (APOE4) is the most important genetic risk factor for Alzheimer’s disease, associated with an approximately eight-fold increased risk for developing the disease, and a more than 15 years earlier disease onset among homozygous carriers." (PMID 27699079, 2016). "Apolipoprotein E4 (ApoE4) is a major genetic risk factor for Alzheimer disease (AD)." (PMID 27171180, 2016). "In addition, PMEL amyloid formation is regulated by ApoE and sensitive to ApoE isoforms, the ApoE E4 gene variant being the major known genetic risk factor for late-onset Alzheimer’s disease." (PMID 27589732, 2016). "All of these evidences manifested that ApoE-ε4 allele could be a vital factor in the Alzheimer's disease caused by CHAT rs3810950 polymorphism." (PMID 27597977, 2016). "A further stratified analysis of the association between CHAT rs3810950 allele and Alzheimer's disease according to the ApoE-ε4 status showed that, with the same rs3810950 polymorphism, ApoE-ε4 carriers exhibited a significantly higher incidence of AD than the non-ApoE-ε4 carriers." (PMID 27597977, 2016). "In addition, a higher risk for VCI has been reported in carriers of the Apolipoprotein E (ApoE) ε4 allele, which is the major genetic risk factor for Alzheimer’s disease (AD) dementia." (PMID 27176617, 2016). "The Apolipoprotein E (APOE) gene has a strong association with Alzheimer’s disease (AD)." (PMID 27468260, 2016). "The apolipoprotein E4 (ApoE4) is the strongest genetic risk factor for Alzheimer’s disease (AD)." (PMID 27189808, 2016). "In this study we were able to compare the significance of hopelessness in midlife versus later life for cognitive impairment in later life and to relate these associations both to depressive symptoms and to the main genetic risk factor for Alzheimer’s disease, the apolipoprotein E4 allele (ApoE4)." (PMID 26460971, 2015). "Apolipoprotein E (ApoE) allele is a well-known genetic risk factor for Alzheimer disease." (PMID 25671598, 2015). "Indeed, even if this paper focused on the impact of ApoE on lipid concentrations, ApoE is a well-known risk factor for many diseases including Alzheimer's disease." (PMID 26605088, 2015). "ApoE is a lipid transporter protein associated with the onset of Alzheimer’s disease." (PMID 26506597, 2015). "In this respect, ApoA-I may have actions analogous to apolipoprotein E (ApoE) where common genetic variants have directly opposing effects on β-amyloid deposition and clearance and therefore risk for Alzheimer’s disease." (PMID 26582989, 2015). "In addition to coronary artery disease, ApoE gene polymorphisms were in relationship with many other diseases, including Alzheimer's disease, DM, Parkinson's disease, renal disease, and stroke." (PMID 26380146, 2015). "In addition, 60% of patients who are carriers of the APOE-e4 allele show a higher risk factor for Alzheimer's disease (AD) when the virus is present." (PMID 26649202, 2015). "The ε4 allele of apolipoprotein E (APOE ε4) is a well-established risk factor for Alzheimer’s disease (AD), and may confer anatomic and functional effects years before clinical signs of cognitive decline are observed." (PMID 25738563, 2015). "The prior study indicated that the APOE ε4 carriers had significant decreases in cerebral metabolic rate for glucose (CMRgl) in cingulate cortex and parahippocampal, which was associated with the predisposition to Alzheimer’s dementia." (PMID 26161964, 2015).
Alzheimer disease (continued). "Apolipoprotein E (ApoE) genotype is the strongest predictor of Alzheimer’s Disease (AD) risk." (PMID 25688974, 2015). "Baseline ADAS-Cog13 (The Alzheimer's Disease Assessment Scale) score was associated with CSF ferritin (P=0.006), ApoE levels (P=0.0003) and tau/Aβ1–42 ratio (P=0.025), independently, in a multiple regression model containing the AD biomarkers and other clinical variables." (PMID 25988319, 2015). "It is unclear how human apolipoprotein E4 (ApoE4) increases the risk for Alzheimer’s disease (AD)." (PMID 26346625, 2015). "Functional connectivity in default mode network (DMN) may be changed in Alzheimer’s disease (AD) patients and related risk populations, such as amnestic mild cognitive impairment (aMCI) patients and APOE ε4 carriers." (PMID 26177270, 2015). "APOE is linked to Alzheimer’s disease, and this study suggests that there may be limited insight to be gained from studies of APOE regulation that are not conducted in specific brain regions." (PMID 24555763, 2014). "For example, based on the linkage disequilibrium structure of APOE, as well as available HapMap data, one could accurately predict Alzheimer’s disease risk for an individual even after removal of the individual’s APOE genotypes from the analysis." (PMID 25153467, 2014). "Because BBB is a site for brain Aβ clearance to the blood, apoE-isoform-specific regulation of BBB function(s) may explain the mechanism underlying apoE4-accelerated development of Alzheimer disease." (PMID 25197575, 2014). "Apolipoprotein E is the primary lipid transporter in brain tissue with carriers of the APOE4 allelic variant at several fold increased risk of Alzheimer’s disease (~three- and ~15-fold increase in risk in APOE3/E4 and APOE4/E4, respectively, relative to the wild-type genotype)." (PMID 25054550, 2014). "The E4 allele of ApoE increases the risk of developing sporadic forms of Alzheimer's disease." (PMID 25405877, 2014). "For example, both TOMM40 and APOE were known to be linked to Alzheimer's disease." (PMID 25098835, 2014). "In addition to cardiovascular disease, apoE gene polymorphisms were associated with many pathophysiological conditions, including Alzheimer’s disease (AD), diabetes,Parkinson’s disease, renal disease and stroke." (PMID 24755673, 2014). "Given the important role of APOE variants in late-onset Alzheimer's disease, we first looked at the APOE ε4 allele as defined by the ancestral alleles rs429358-C and rs7412-C (130Arg and 176Arg) and APOE ε2 allele as defined by rs429358-T and rs7412-T (130Cys and 176Cys)." (PMID 25333069, 2014). "APOE allele epsilon 4 is closely related to Alzheimer’s disease." (PMID 24608522, 2014). "In 1994, genetic testing for late-onset Alzheimer's disease became available primarily in research settings, offering patients a probabilistic measure of their risk for the disease by analyzing their apolipoprotein E (ApoE) genotype." (PMID 24010759, 2013). "Similarly, for carriers of the apolipoprotein E ε4 allele (a known risk factor for Alzheimer’s disease) regular physical activity has been demonstrated to be advantageous for efficient stimulus processing in a working memory task." (PMID 23700461, 2013). "Genetic risks, such as carrying the APOE-4 allele, contribute to brain structure changes that may render people at higher risk of developing Alzheimer's disease." (PMID 24228185, 2013). "In addition, the intronic region surrounding rs4073366 is complementary to APOE mRNA and has been associated with decreased risk of Alzheimer’s disease (AD) in males carrying the APOE ε4 allele." (PMID 23883350, 2013). "The apolipoprotein E (ApoE) is also the main apolipoprotein in the central nervous system, with evidence of its association with cerebrovascular diseases, and neurodegenerative diseases as late onset of Alzheimer's Disease (AD) and PD." (PMID 24175296, 2013).
Alzheimer disease (continued). "Change in hippocampal volume is not only associated with risk for AD, but may also be mediated by risk genes for Alzheimer’s disease such as APOE, as well as affected by risk factors such as a maternal family history of AD." (PMID 24040196, 2013). "Upregulation of apolipoprotein E has already been described in activated astrocytes in Alzheimer′s and prion disease and is considered as one of the strongest genetic risk factors in Alzheimer disease." (PMID 23210548, 2012). "In fact, when variants with particularly large effects do exist—such as APOE in Alzheimer’s disease, BRCA1 and BRCA2 in breast and ovarian cancer, and LRRK2 in Parkinson’s disease —previous authors have suggested simulations in lieu of their analytical approximation." (PMID 22827772, 2012). "Apolipoprotein E (ApoE) represents a major risk factor locus for late onset Alzheimer's disease." (PMID 22956959, 2012). "APOE ε4 is currently the strongest genetic risk factor for developing Alzheimer’s disease (AD)." (PMID 22675504, 2012). "The apolipoprotein E4 (ApoE4) is an established risk factor for Alzheimer's disease (AD)." (PMID 22558310, 2012). "In fact, fewer than 30% of people with the APOE ε4 polymorphism develop Alzheimer's disease." (PMID 22958637, 2011). "We conducted a series of FLIM-FRET experiments using human postmortem tissue sections obtained from the Massachusetts Alzheimer Disease Research Center (ADRC) brain bank to examine ApoE conformation when it is associated with senile plaques in situ in the Alzheimer brain." (PMID 21297948, 2011). "It is well established that the risk of Alzheimer's disease is increased in APOE ε4 carriers." (PMID 22110642, 2011). "Both VLDLR and ApoER2 are receptors for apolipoprotein E (apoE), the leading genetic risk factor for Alzheimer's disease (AD), and these receptors may play different roles in modulating the risk associated with apoE." (PMID 21554715, 2011). "APOE genotype is associated with the risk of Alzheimer's disease." (PMID 22110642, 2011). "However, APOE genotype is a proven risk factor for Alzheimer's disease and cognitive impairment in old age." (PMID 22110642, 2011). "This risk may be modulated through the apolipoprotein E ɛ4 (ApoE4) genotype, a known genetic risk for the development of Alzheimer’s Disease." (PMID 21139859, 2010). "Proteins expressed by HSV-1 are homologous to all of the protein products of the major susceptibility gene in Alzheimer's disease (APOE, clusterin, complement receptor 1, and PICALM) as well as to APP and tau and over 100 others implicated in genetic association studies." (PMID 21234306, 2010). "The two-SNP haplotype that was most strongly associated with ALS in the joint analysis (rs3849942-rs10122902) mimics the behaviour of the APOE association with Alzheimer's disease; the three APOE alleles—ɛ2, ɛ3, and ɛ4—are in fact pairs of alleles at two SNPs forming a haplotype." (PMID 20801717, 2010). "Apolipoprotein E allele ε4 (apoE4) is a strong risk factor for developing Alzheimer's disease (AD)." (PMID 19695092, 2009). "Finally and intriguingly, mammals other than humans seem to have just one allelic form of APOE, the E4 allele, the same form in humans predisposes carriers to a much higher risk of Alzheimer's disease." (PMID 18837980, 2008). "For instance in the case of Alzheimer's disease (AD), individuals that are homozygous or heterozygous for ApoE ε4, have a significantly increased risk of developing the disease with an earlier onset compared with individuals with the most common ApoE ε3/ε3 genotype." (PMID 18823563, 2008). "It has been shown that the prevalence of Alzheimer's disease (AD) is associated with the polymorphisms of genes related to cholesterol metabolism, including apolipoprotein E (apoE), ATP-binding cassette transporter A1 (ABCA1), and CYP46, the gene encoding cholesterol 24-hydroxylase." (PMID 17504523, 2007).
Alzheimer disease (continued). "In addition to a significant association between the APOE gene and Alzheimer's disease, subgroup analyses revealed an association with subtypes based on age of onset, family history, and sex." (PMID 16603077, 2006). "More than a decade has passed since apolipoprotein E4 (APOE-ε4) was identified as a primary risk factor for Alzheimer 's disease (AD), yet researchers are even now struggling to understand how the apolipoprotein system integrates into the puzzle of AD etiology." (PMID 17062143, 2006). "Despite increasing interest in sleep–Alzheimer’s disease interactions, few studies examined astrocytic biomarkers in relation to sleep, and even fewer have considered how common risk factor such as age and APOE ε4 may moderate these associations." (PMID 41268178, 2025). "We have published previously that murine prion disease shows many of the molecular hallmarks of Alzheimer’s disease (AD), including the accumulation and spread of disease-causing misfolded protein, neuroinflammation and an up-regulation of protein markers of AD, for example, Apolipoprotein E." (PMID 39958854, 2025). "Overall, this study reports newly identified and previously uncharacterized high-risk ApoE variant, L122P, contributing to altered Aβ binding and structural destabilization, and offers insights for precision-medicine approaches targeting variant-specific mechanisms in Alzheimer’s disease." (PMID 40892789, 2025). "Furthermore, ApoJ may act in conjunction with other genetic risk factors, such as ApoE, and this in turn may play a role in the development and progression of post-ischemic neurodegeneration and Alzheimer’s disease." (PMID 41516203, 2025). "Furthermore, we sought to determine whether these putative associations were modulated by Alzheimer’s disease risk factors such as older age, female sex and apolipoprotein E (APOE)-ɛ4." (PMID 39723106, 2025). "For instance, the APOE ε4 allele is associated with increased neurofibrillary tangles in females compared with males, which may explain why female APOE ε4 carriers are at higher risk of developing Alzheimer’s disease than male carriers." (PMID 39901234, 2025). "Notably, several Alzheimer’s disease (AD)-associated genetic risk variants—including APOE ε4, TREM2 R47H (rs75932628), CD33 rs3865444-C, INPP5D regulatory variants, MS4A6A locus variants, and PLCG2 P522R (rs72824905)—are enriched in microglia and influence their functional state." (PMID 40934003, 2025). "Apolipoprotein E (ApoE) is a key protein involved in lipid transport, neuronal regeneration, and inflammation regulation, and in recent years, it has been found to be closely associated with neural repair in Alzheimer’s disease, cerebral hemorrhage, and traumatic brain injury." (PMID 41394006, 2025). "Notably, ApoE involvement in MAMs has been linked to the development of neurodegenerative diseases, such as Alzheimer's disease, in which mitochondrial Ca2+ overload and increased SR-mitochondria Ca2+ coupling are key triggers of the cell death-induced neurodegeneration." (PMID 40492240, 2025). "This study investigates the interaction between sleep duration and Apolipoprotein E genotype on the functional connectivity of the locus coeruleus in clinically unimpaired older adults with elevated amyloid beta, a population at risk for pre-clinical Alzheimer’s disease." (PMID 40994826, 2025). "In addition, patients with Alzheimer’s disease have abnormal insulin metabolism associated with the apolipoprotein E,33 corroborated by reports of reduced hippocampal insulin-degrading enzyme (an amyloid-β-degrading metalloprotease) in APOE-ε4 carriers." (PMID 40834163, 2025). "With actionability of Alzheimer’s Disease on the horizon, our results encourage engaging a discussion on whether reporting these variants to patient-carriers is desirable, possibly in combination with APOE genotype." (PMID 41327266, 2025).
Alzheimer disease (continued). "To evaluate the influence of Alzheimer’s disease-related risk factors on olfactory-guided behavior, we assessed odor preference, anhedonia-like responses, and exploratory dynamics in mice stratified by APOE genotype, age, sex, diet, and immune background (hNOS2 vs. mNos2)." (PMID 40661485, 2025). "APOE genotyping is uniquely positioned at the intersection of pharmacogenetics and germline testing: it provides insight not only into drug safety (specifically the risk of Amyloid-Related Imaging Abnormalities) but also into familial risk for developing Alzheimer’s disease." (PMID 40761402, 2025). "Some studies suggest that low cholesterol levels are associated with cognitive decline, while others argue that high cholesterol levels may be an independent risk factor for Alzheimer’s disease, with the ApoE ε4 allele potentially mediating this effect through cholesterol." (PMID 40563435, 2025). "The APOE (apolipoprotein E) ε4 allele is thestrongest known genetic risk factor for sporadic Alzheimer disease (AD) andfor brain amyloidosis, an early marker of disease pathophysiology." (PMID 40703204, 2025). "The APOE ε2 allele (encoded by the rs7412 SNP) is protective for incident Alzheimer’s disease, the APOE ε4 allele (encoded by rs429358) increases risk, and together the interplay between these two SNPs exerts an important influence on genetic susceptibility to Alzheimer’s disease." (PMID 41366417, 2025). "The APOE variant, rs429358, was associated with age, which might be explained by age-dependent selection or survival effects due to this variant’s association with Alzheimer’s disease and early mortality." (PMID 39609904, 2024). "Because APOE is an important risk gene for Alzheimer’s disease, we also considered APOE genotype as a covariate in statistical analyses, the result showed that brain regions with EC and DC differences remained unchanged after APOE genotype was added to the covariate." (PMID 38425749, 2024). "Additionally, the effect of apolipoprotein E (APOE) ε4, a strong genetic risk factor for Alzheimer’s disease, on cerebral blood flow and cerebrovascular function remains unclear." (PMID 39625920, 2024). "Sex differences often suggest a role of sex hormones, and in Alzheimer’s Disease (AD) research, women show higher disease prevalence, accelerated cognitive decline, and an enhanced effect of the strongest genetic risk factor for AD, the apolipoprotein E ε4 allele (APOE-ε4)." (PMID 38835072, 2024). "Interestingly, in our autopsy studies, apolipoprotein E allele 4 (APOE4) carriers of the strongest Alzheimer's disease genetic risk factor had higher AD Braak stages and the highest risk for suicide associated with lower cumulative exposures to PM2.5 vs. APOE3 carriers." (PMID 36923490, 2023). "Sex differences are established in associations between apolipoprotein E (APOE) ε4 and cognitive impairment in Alzheimer disease (AD)." (PMID 37459083, 2023). "However, type 2 diabetes was significantly associated with all-cause dementia (except for Alzheimer’s disease) in APOE ε4 carriers when taking into account the competing risk of Alzheimer’s disease, with a subhazard ratio (sHR) of 1.49, 95% confidence interval (CI) 1.05–2.11, P = 0.025." (PMID 37091584, 2023). "Additionally, studies investigating cerebrovascular haemodynamics should measure apolipoprotein‐E4 (APOE‐4) status, a genetic risk factor for Alzheimer's disease, which further accelerates age‐related changes in biomarkers of Alzheimer's disease in perimenopausal and postmenopausal women." (PMID 36808648, 2023). "The ApoE gene has specific relevance to memory function in the central nervous system, and its expression regulation and gene polymorphisms are closely related to neurological or neurodegenerative diseases such as Alzheimer’s disease, Parkinson’s disease, and hyperlipidemia." (PMID 37644506, 2023).